TPO (thyroid peroxidase)
Diseases named in the same sentence as TPO in open-access papers (continued):
Sharing a sentence is not in itself a finding about the gene and the disease.
congenital hypothyroidism (continued). "On the other hand, the finding of a homozygous deletion of exons 11 to 15 in the TPO gene in patients with congenital hypothyroidism in a Pakistani family has been reported." (PMID 39064575, 2024). "Another interesting example of a combination with less evident proof is the oligogenic combination OLI474, associated with congenital hypothyroidism, derived from a cohort study and involving three heterozygous variants in the genes DUOX2, TG and TPO." (PMID 35411390, 2022). "In our previous studies, we have demonstrated the association of certain variants of the thyroid-stimulating hormone receptor (TSHR), thyroid peroxidase (TPO), and thyroglobulin (TG) genes with congenital hypothyroidism." (PMID 34638176, 2021). "As a crucial enzyme in thyroid hormone synthesis, the genetic defective thyroid peroxidase (TPO) was one of the main genetic factors leading to congenital hypothyroidism (CH)." (PMID 35002963, 2021). "Studies have also shown an indirect relationship of Gαq/11 activation to thyroid peroxidase formation and a congenital hypothyroidism phenotype." (PMID 32676053, 2020). "The incidence of congenital hypothyroidism due to homozygous TPO defects has been estimated at 1:66.000 for a Dutch population." (PMID 26761947, 2016). "In conclusion, this single disulfide bond loss mutation of a new TPO homozygous mutation, p.Cys655Phe, reduced TPO activity and caused congenital hypothyroidism without affecting subcellular localization of TPO proteins." (PMID 32908504, 2020). "This single disulfide bond loss mutation reduced TPO activity and caused congenital hypothyroidism without affecting subcellular localization of TPO proteins." (PMID 32908504, 2020). "In the present study, the whole gene scanning of TPO gene by SSCP and sequencing was performed in 41 patients with permanent congenital hypothyroidism due to dyshormonogenesis." (PMID 22919382, 2012). "When TPO activity is not normal or is totally absent, thyroid iodide organification may occur giving rise to congenital hypothyroidism." (PMID 31366075, 2019).
depression (30 papers, 2005 to 2026). "A positive TPO-ab status was associated with an increased risk for first-onset depression at four months postpartum (adjusted OR: 3.8; 95% CI: 1.3–11.6), but not at other postpartum time points." (PMID 38732283, 2024). "(2012) reported that thyroid peroxidase antibodies were positively associated with trait markers of depression." (PMID 38189637, 2024). "Multivariate logistic regression analysis revealed that the anti-TPO value was a significant independent risk factor for the presence of depressive disorder (adjusted odds ratio (OR) = 1.002, 95% confidence interval (CI) 1.001-1.004, p < 0.011)." (PMID 38094874, 2023). "Multivariate logistic regression analysis revealed that the anti-TPO value was the most significant independent risk factor for the presence of depressive disorder (p < 0.01)." (PMID 38094874, 2023). "Thyroid autoimmunity, especially anti-TPO, is also associated with a decline in quality of life and increased depression." (PMID 36506504, 2022). "Participants and methods: Paired serum and CSF samples from 100 patients with unipolar depression were examined for anti-TPO and anti-TG antibodies using enzyme-linked immunosorbent assays." (PMID 32726952, 2020). "Multivariate logistic regression analysis revealed SCH, Graves’ eye syndrome and high serum TPO antibody level as risk factors for depression." (PMID 27135245, 2016). "The findings obtained suggest the need for further longitudinal studies aimed at clarifying the association between anxiety and depressive disorders and anti-TPO+." (PMID 16285879, 2005). "In addition, in another study investigating the quality of life in 84 patients with HT, it was reported that high Anti-TPO levels were associated with an increased risk of depression, even in euthyroid patients." (PMID 38892793, 2024). "High titer anti-TPO and anti-Tg levels are significantly and negatively correlated with quality of life, and high anti-TPO levels are positively correlated with depression risk." (PMID 36506504, 2022). "Further, the detection of anti-thyroid peroxidase and anti-thyroglobulin autoantibodies in the cerebrospinal fluid of patients with unipolar depression reinforces the potential role of immune mechanisms in psychiatric conditions beyond thyroid dysfunction." (PMID 39717384, 2024). "Both anti-TPO antibody titres and autonomic function correlated to scales of anxiety, depression and quality of life as well." (PMID 38811750, 2024). "In a study conducted on adults in Germany, pathologically increased anti-TPO levels were found to be significant among patients with depression and schizophrenia." (PMID 38094874, 2023). "Our results show only the relationship of anti-TPO with mood and emotional condition through regression analysis of the questionnaire scores obtained in relation to depressive disorder." (PMID 38094874, 2023). "Most depressed patients had a high level of antithyroid peroxidase (anti-TPO) antibody levels, so it may have diagnostic value in AIT and depression." (PMID 39280013, 2024). "However, for some authors, the status of thyroid peroxidase antibodies has become considered a marker of vulnerability to depression." (PMID 35351167, 2022). "A positive anti-TPO state was associated with an increased risk of self-reported depression of a single onset at four months postpartum but not at other postpartum time points." (PMID 35351167, 2022). "However, in a multivariate model the TPO-abs level was related to goitre symptoms, depression and anxiety." (PMID 34027377, 2021). "Discussion: A subgroup of seropositive patients showed intrathecal synthesis of anti-TPO and, more rarely, of anti-TG antibodies, which might be an indication of central autoimmunity in a subgroup of patients with unipolar depression." (PMID 32726952, 2020).
depression (continued). "Elevated ASIs are interesting biomarkers in neuropsychiatric diseases (compare with their established use, e.g., in Lyme neuroborreliosis), but the role of elevated ASIs for anti-TPO and anti-TG antibodies in patients with unipolar depression requires further intensive research." (PMID 32726952, 2020). "The presence of thyroid peroxidase antibodies (TPO-ab) during early gestation is predictive of both autoimmune thyroid disorders and depression." (PMID 38732283, 2024). "TPO: thyroid peroxidase; Tg: thyroglobulin; CDI: Children’s Depression Inventory; SCARED: Screen for Child Anxiety-Related Emotional Disorders." (PMID 38094874, 2023). "SCH: subclinical hypothyroidism; MDD: major depressive disorder; BMI: basal metabolic index; TSH: thyroid stimulating hormone; TPO-Abs: thyroid peroxidase antibodies." (PMID 36003348, 2022). "Our results are similar to results from other studes that claim that elevated TPO antibody levels are not indicators of depression." (PMID 37582108, 2023). "Although some authors consider the status of positive anti-TPO antibodies to be a possible marker of vulnerability to depression, it is not yet possible to conclude which are the mechanisms of thyroid function involved in the pregnancy-puerperal cycle and PPD." (PMID 35351167, 2022). "At postpartum, depression scores (EPDS, BDI) correlated positively with rT3 concentrations while scores derived from the BLUES questionnaire showed a trend of positive correlation with anti-TPO concentrations." (PMID 34421508, 2021).
infertile (28 papers, 2013 to 2025). "Anti-TPO is frequently detected in euthyroid women undergoing infertility workup and has been implicated in adverse reproductive outcomes including miscarriage, subfertility, and poor in vitro fertilization (IVF) response." (PMID 41303060, 2025). "Anti-TPO testing can enhance infertility risk stratification as part of a multifactorial evaluation but should not be used in isolation for diagnostic purposes." (PMID 41303060, 2025). "By summarizing and analyzing the latest studies since the 2017 guidelines, this review documented that anti-TPO antibodies were associated with infertility in subsets of women, mainly in those with unexplained infertility or polycystic ovarian syndrome (PCOS), but not in all women." (PMID 35351031, 2022). "The study recommends routine anti-TPO antibody screening for infertile women under 35, even with normal thyroid hormone levels." (PMID 41303060, 2025). "Antithyroid antibodies, specifically those targeting thyroid peroxidase (anti-TPO) and thyroglobulin (anti-Tg), have garnered attention concerning their potential associations with infertility." (PMID 40981275, 2025). "Anti-TPO positivity, present in 18.4% of our cohort, closely parallels rates reported in other studies examining infertile populations, where estimates range from 18% to 27%." (PMID 41303060, 2025). "Seventy-four previously infertile women were diagnosed with anti-TPO antibody levels >100 IU/l and were followed up during pregnancy." (PMID 37869413, 2023). "Among the 177 infertile women and the 171 controls originally recruited, the serum levels of TSH and of anti-TPO of 154 infertile women and 155 control women were available at two different times, each 2–4 weeks apart." (PMID 37869413, 2023). "Several data demonstrated significantly higher levels of thyroid antibodies in infertile women with lower ovarian reserves, and this seems particularly true for anti-TPO Abs." (PMID 37635968, 2023). "Although these lower threshold levels were later revoked, they are still recommended in infertile women prior to treatment with ART or in the presence of anti-TPO." (PMID 37869413, 2023). "This study aimed to find out the prevalence of positive thyroid peroxidase antibodies among women with polycystic ovarian syndrome visiting an infertility clinic at a tertiary care centre." (PMID 38289756, 2023). "The primary objective was to find out the prevalence of positive thyroid peroxidase antibodies among women with polycystic ovarian syndrome visiting an infertility clinic at a tertiary care centre." (PMID 38289756, 2023). "In euthyroid patients, 49.5% replied that treatment with thyroid hormones was never indicated, while 47.3% would consider L-T4 for euthyroid infertile women with high thyroid peroxidase (TPO) antibody levels." (PMID 34938274, 2021). "Infertility, anemia, and premature birth were all more common in anti-TPO-positive euthyroid females." (PMID 34667679, 2021). "The strength of this study is evaluation of anti- TPO positive test in women with complaint of infertility." (PMID 33178853, 2020). "The limitation was the small sample size, which was restricted in the anti-TPO positive women with infertility complaint." (PMID 33178853, 2020). "A researcher reported a study with about 5000 infertile women and presented positive anti-TPO in 9.8%-12.1% that is higher in low ovarian reserve patients." (PMID 33178853, 2020). "In unselected populations of women, its reported prevalence ranges from 4% to 20%; however, in women with recurrent miscarriages and infertility, TPO Ab prevalence is usually higher, 14–33%." (PMID 29273014, 2017). "This study aims to investigate the association between anti-TPO positivity and ovarian reserve markers—antral follicle count (AFC), anti-Müllerian hormone (AMH), and follicle-stimulating hormone (FSH)—in euthyroid infertile women." (PMID 41303060, 2025). "Research has found a significant correlation between TPO-AB and infertility in patients with PCOS." (PMID 38383330, 2024).
infertile (continued). "In the final multivariate model, abnormal TPO-antibodies and/or TG antibodies (OR 13.099, 95%CI 2.382-72.044; p= 0.003) and the presence unexplained infertility (OR 4.906, 95% CI 1.181-20.388; p= 0.029) were independently associated with an increased chance for ferritin levels <30μg/L." (PMID 37361544, 2023). "Moreover, our survey, as the majority of THESIS surveys, identified similar trends and deviations in the treatment with TH, as the treatment of euthyroid TPO+ infertile women and the preference for combined LT4 + LT3 treatment in hypothyroid patients with persistent symptoms." (PMID 35248144, 2022). "In a retrospective cohort study conducted on 196 infertile women with PCOS, anti-TPO Ab levels exceeding the upper reference limit were found in significantly more CC-resistant patients versus CC responders or metformin responders." (PMID 37635968, 2023). "First, we studied in infertile women the accuracy and the reproducibility of preconception thyroid gland screening based on TSH and anti-TPO." (PMID 37869413, 2023). "Second, the impact of distinct setpoints of TSH in preconception (with or without anti-TPO) was monitored during pregnancy in 87 previously infertile women by high-frequency monitoring of thyroid function." (PMID 37869413, 2023). "The number of cases presenting with TSH levels at the given cut-off levels and with or without anti-TPO antibody levels >100 IU/ml was compared in 177 patients presenting with infertility and in 171 control women." (PMID 37869413, 2023). "The odds of being diagnosed with subclinical hypothyroidism at both TSH threshold levels (either 2.5 or 4.5 mIU/l, with or without anti-TPO) were similar among infertile women and control women not aiming for pregnancy." (PMID 37869413, 2023). "Patients with positive anti-TPO antibody findings who have not yet completed their family should be aware of their lower reproductive life span before seeking medical consult for infertility." (PMID 33178853, 2020). "We conclude that the odds of being diagnosed with subclinical hypothyroidism, with or without anti-TPO antibodies, were similar in infertile women versus comparable aged controls currently not aiming for pregnancy, regardless of lower or higher threshold values of TSH." (PMID 37869413, 2023). "In addition, a group of previously infertile women with known preconception setpoints of TSH (with or without anti-TPO) were followed up prospectively throughout pregnancy and after birth." (PMID 37869413, 2023). "The TPO median(IQR) of women with and without a history of infertility were 6.05 (3.30–13.96)and 6.04 (3.17–11.15);(P = 0.613), they were 5.08 (3.20–125.68) and 5.31 (3.93–125.68);(P = 0.490) in male participants, respectively." (PMID 34034716, 2021).
papillary thyroid carcinoma (28 papers, 2004 to 2025). "Interestingly, a previous study has shown increased risk of differentiated thyroid carcinoma in European populations with certain TPO gene variants." (PMID 34501348, 2021). "TPO may be useful in confirming or ruling out benign diseases from differentiated thyroid carcinoma, with the exception of low-risk carcinoma such as MIFC." (PMID 26300979, 2015). "Here, we describe the generation and characterization of six novel BRAFV600E-driven papillary thyroid cancer (PTC) cell lines established from a BrafV600E+/−/Pten+/−/TPO-Cre mouse model that spontaneously develop thyroid tumors." (PMID 36765847, 2023). "The objective of this study was to investigate the expression of thyroid peroxidase (TPO) in papillary thyroid carcinoma (PTC) and to preliminarily investigate its value as a marker of lymph node metastasis and recurrence in patients with PTC." (PMID 37407700, 2023). "Papillary thyroid carcinomas developed in BrafV600E+/−/Pten+/−/TPO-Cre mice of a pure 129SvJ genetic background (cell lines BB19, BB57, BB342, and BB1845) or a mixed genetic background (cell lines B1865 and B1866)." (PMID 36765847, 2023). "Thyroglobulin and TPO are the main immunological target in HT and analogically also in the immune response in papillary carcinoma." (PMID 33991306, 2021). "The scarce TPO staining of PTC in our series is consistent with other reports that show strong TPO suppression in papillary carcinomas." (PMID 26300979, 2015). "Increased TPO expression in benign lesions as compared to decreased expression in papillary carcinomas and undifferentiated tumors is outstanding." (PMID 26300979, 2015). "Microscopic foci of papillary carcinoma were seen in two resections, although the benign TPO-positive biopsies had given morphological evidence of a benign goitre." (PMID 18031322, 2008). "TPO content has been shown to be significantly lower in thyroid malignancies as compared to benign conditions and normal tissue; also, a reduction in TPO activity and TPO mRNA of 55–70 % is observed in differentiated thyroid carcinoma (DTC)." (PMID 26300979, 2015). "In this report, we studied thyroid papillary cancer in mice with a thyroid-specific knock-in of oncogenic Braf [LSL-Braf(V600E)/TPO-Cre] in order to determine if stemness was present in such tumors and whether EMT was the source of such characteristics." (PMID 25076938, 2014). "Thereafter, the ability of recombinant and circulating anti-TPO aAbs to lyse papillary thyroid cancer cells was explored using systems detecting ADCC with the monocyte cell line HL-60 and PBMC as effector cells and NPA cells as targets, because 100% of these cells express TPO on their cell surface." (PMID 20145622, 2010). "We show here that anti-TPO aAb B4′ purified from CHO is able to induce a moderate cytotoxic activity, lower than that of patients' circulating anti-TPO aAbs on the papillary carcinoma cell line NPA, whatever the effector cells used (peripheral blood mononuclear cells (PBMC) or monocyte cell line)." (PMID 20145622, 2010). "We demonstrated the expected variability of the observed TPO cfRNA level peri-operatively and under thyroid stimulating hormone (TSH) stimulation for adjuvant RAI therapy in a patient (CBN049) with Stage I papillary thyroid carcinoma [T3N0M0]." (PMID 34512731, 2021). "The expressive levels of miR-200a-5p, TPO, CD56, Galectin-3, MC, CK19 and B-raf in benign thyroid tumors with papillary hyperplasia and papillary thyroid carcinoma." (PMID 30005075, 2018). "Correlation analysis of the expressions of has-miR-200a-5p to TPO, CD56, Galectin-3, MC, CK19 and B-raf in papillary thyroid carcinoma." (PMID 30005075, 2018). "We studied the cytotoxic activity of anti-thyroperoxidase autoantibodies (anti-TPO aAbs, expressed in baculovirus/insect cell (B4) and CHO cells (B4′) or purified from patients' sera) against a papillary thyroid cancer (NPA) cell line." (PMID 20145622, 2010).